AFP (alpha fetoprotein)
Diseases named in the same sentence as AFP in open-access papers (continued):
Sharing a sentence is not in itself a finding about the gene and the disease.
hepatocellular carcinoma (continued). "Moreover the clinical usefulness of alpha-fetoprotein in hepatocellular carcinoma management is still being debated." (PMID 17288606, 2007). "Synthesis of AFP is dramatically reduced in adulthood but can resume in case of liver pathologies (cirrhosis, hepatitis...) or of tumors such as hepatocellular carcinoma, germ cell tumors (embryonic carcinoma and teratocarcinoma) and some pancreatic and renal tumors." (PMID 19690639, 2007). "AFP is used as a serum marker for diagnosis of hepatocellular carcinoma." (PMID 16822301, 2006). "Take together all findings, we propose that the effect of AFP in the escape of hepatoma Bel 7402 cells from immune surveillance is achieved though decreasing Fas in its membrane and secreting FasL which in turn to trigger apoptosis of lymphocytes via caspase-3 cascade." (PMID 16080799, 2005). "Thus revealing the intracellular mechanisms underlying the evasion of tumor from host immune surveillance will provide further insights into the understanding for the biological role of AFP, particularly in the case of hepatocellular carcinomas." (PMID 16080799, 2005). "However, the over-expression of AFP in human hepatoma cells is concurrent with aberrant growth manifestation." (PMID 16080799, 2005). "Application of this test for the 'hepatoma-specific' AFP markedly increases the positive predictive value of AFP and, in some cases, permits the presence of tumour to be inferred before it could be detected by routine ultrasound examination." (PMID 9010032, 1997). "In hepatocellular carcinomas, cFN was also compared with alpha-fetoprotein." (PMID 9310245, 1997). "However, alpha-L-fucosidase was both less sensitive (75 versus 87%) and less specific (70 versus 87%) than alpha-fetoprotein as a serum marker of hepatocellular carcinoma." (PMID 2467686, 1989). "Hepatocellular carcinoma (HCC) originates from stem cells, and alpha‐fetoprotein (AFP) is a key biomarker for HCC." (PMID 40979569, 2025). "Similarly, in hepatocellular carcinoma (HCC), a serum-based metabolite panel was identified in metabolic syndrome-positive cases and was proposed as a diagnostic tool with improved accuracy compared with AFP." (PMID 41236698, 2025). "AFP is widely recognized as a significant biomarker for liver cancer, particularly hepatocellular carcinoma (HCC), and its utility has been demonstrated in various clinical settings." (PMID 40430002, 2025). "Given that AFP is a key tumor marker for hepatocellular carcinoma (HCC), and considering her 30-year history of chronic hepatitis B with ongoing antiviral therapy, a primary or metastatic hepatic malignancy was strongly suspected." (PMID 40919162, 2025). "used magnetic resonance imaging and alpha-fetoprotein (AFP) levels to evaluate residual lesions after RT in hepatocellular carcinoma (HCC)." (PMID 40821802, 2025). "Increased fucosylation of alpha-fetoprotein has also been noted in the sera of patients with early hepatocellular carcinoma (HCC) and germ cell tumors, providing an early marker of tumor formation and metastasis and reoccurrence after curative treatment." (PMID 40725456, 2025). "For example, alpha-fetoprotein (AFP) became a popular serum indicator of hepatocellular carcinoma (HCC)." (PMID 40870868, 2025). "Alpha-fetoprotein (AFP), a glycoprotein produced primarily in the fetal liver and yolk sac, is one of the most widely used biomarkers for hepatocellular carcinoma (HCC) and germ cell tumors (GCTs)." (PMID 41294739, 2025). "In addition, PANDAR was highly expressed in hepatocellular carcinoma tissues and cell lines, and its level was positively correlated with liver cirrhosis, hepatitis B surface antigen (HBsAg), alpha-fetoprotein (AFP), tumor nodule formation, vascular infiltration and TNM staging." (PMID 40713854, 2025).
hepatocellular carcinoma (continued). "Existing models to predict recurrence-free survival (RFS) after hepatectomy for hepatocellular carcinoma (HCC) rely on static preoperative factors such as alpha-fetoprotein (AFP) and tumor burden score (TBS)." (PMID 40238062, 2025). "For example, in hepatocellular carcinoma (HCC) models, dendritic-cell-derived EVs enriched with alpha-fetoprotein (AFP) elicited robust antigen-specific immune responses, consequently delaying tumor progression and significantly extending survival." (PMID 41050925, 2025). "Hepatoid adenocarcinoma (HAC) is a rare type of extrahepatic cancer, resembling hepatocellular carcinoma (HCC), and often producing alpha-fetoprotein (AFP)." (PMID 40859488, 2025). "AFP is an oncofetal protein and is the most widely used biomarker for hepatocellular carcinoma (HCC)." (PMID 40723883, 2025). "All patients with advance fibrosis or cirrhosis should be put on hepatocellular carcinoma (HCC) surveillance, alpha-fetoprotein & US Liver every six months." (PMID 40103882, 2025). "For the clinical diagnosis of CCA, the carbohydrate antigen 19-9 (CA 19-9), carcinoembryonic antigen (CEA) and alpha-fetoprotein (AFP) are routinely used in the differential diagnosis with hepatocellular carcinoma (HCC)." (PMID 40310432, 2025). "In hepatocellular carcinoma (HCC), α-fetoprotein (AFP) levels inform therapeutic intensity and surveillance intervals, while liver-fibrosis staging determines surgical candidacy and transplant eligibility." (PMID 41256539, 2025). "Elevated AFP levels in specific tumors, particularly hepatocellular carcinoma (HCC), have established it as a vital marker for cancer screening." (PMID 39135041, 2024). "Approximately one-third of hepatocellular carcinoma (HCC) cases are characterized by alpha-fetoprotein (AFP) negativity (AFP-NHCC." (PMID 39175473, 2024). "Lastly, the diagnostic usefulness of the anti-BIRC5 autoantibody for hepatocellular carcinoma (HCC) was evaluated by ELISA in a cohort consisting of an additional 149 AFP-positive hepatocellular carcinoma samples (APHCCs), 95 ANHCCs and 244 NCs." (PMID 38832035, 2024). "The study also established a correlation between hPG80 levels and standard imaging in a cohort of patients with hepatocellular carcinoma (HCC), including patients with alpha-fetoprotein (AFP) < 20 ng/mL." (PMID 38672239, 2024). "For instance, Chen's research pinpointed that hybrid and mesenchymal CTC proportions in patients with hepatocellular carcinoma (HCC) were influenced by factors such as age, Barcelona Clinic Liver Cancer Stage, metastasis, and alpha-fetoprotein levels." (PMID 39227943, 2024). "The prognostic significance of the CRAFITY score (CRP and AFP in ImmunoTherapY) has been demonstrated in hepatocellular carcinoma (HCC) patients receiving immunotherapy." (PMID 38365678, 2024). "Historically, alpha-fetoprotein (AFP) has been well recognized as a serum biomarker for hepatocellular carcinoma (HCC) and some other cancers." (PMID 38397429, 2024). "Increasing evidences suggest that AFP plays an important biological role in the development of hepatocellular carcinoma (HCC)." (PMID 38678117, 2024). "Therefore, AFP is a good target for the treatment of hepatocellular carcinoma." (PMID 39136031, 2024). "This is a promoter specific to hepatocellular carcinoma (HCC), which is a modified version of the AFP promoter." (PMID 39682712, 2024). "Alpha-fetoprotein (AFP) can be helpful in differentiating intrahepatic CCA from hepatocellular carcinoma (HCC) as it has high specificity for diagnosing HCC." (PMID 38398194, 2024). "The α-FAtE score, composed of alpha-fetoprotein, alkaline phosphatase, and eosinophil levels, has been reported as a predictor of prognosis in hepatocellular carcinoma (HCC) patients treated with atezolizumab plus bevacizumab." (PMID 39867887, 2024).
hepatocellular carcinoma (continued). "Under normal conditions, AFP levels in adults are low; however, they increase significantly in cases of primary liver cancer (hepatocellular carcinoma, HCC) and germ cell tumors of the testes and ovaries." (PMID 39685591, 2024). "Background and Objectives: Serum alpha-fetoprotein (AFP) is a recognized affordable oncological marker in patients with hepatocellular carcinoma (HCC)." (PMID 38792876, 2024). "AFP may be useful for not only hepatocellular carcinoma but also CRC." (PMID 38449931, 2024). "In our case, the diagnosis of hepatocellular carcinoma (HCC) was made based on imaging features and a high level of alpha-fetoprotein." (PMID 39345809, 2024). "We report a case of a 67-year-old female who presented with right upper quadrant pain, deranged liver enzymes, elevated tumor markers [alpha-fetoprotein (AFP) and CA 19-9], and a large liver mass on imaging, suspected to be hepatocellular carcinoma (HCC)." (PMID 37753063, 2023). "This meta-analysis aimed to assess the performance of the CRAFITY (CRP and AFP in immunotherapy) score as a prognostic factor in hepatocellular carcinoma (HCC) treated with immunotherapy." (PMID 36915049, 2023). "As one of the most common malignant tumors in clinical practice, hepatocellular carcinoma (HCC) is a major threat to human health, where alpha-fetoprotein (AFP) is widely used for early screening and diagnoses." (PMID 36890811, 2023). "This AFP level has been used by a previous study as a cut off to exclude patients with possible mixed hepatocellular carcinoma-cholangiocarcinoma (HCC-CCA)." (PMID 37404757, 2023). "In addition, AFP is produced at very low levels in healthy individuals, mainly from the liver (<10 ng/mL), and thus, the elevation of its concentration is indicative of malignant diseases and especially of primary hepatocellular carcinoma." (PMID 37241360, 2023). "We have distinguished two basic forms of alpha-fetoprotein: the nAFP (native AFP) plasma protein in fetal circulation and the tAFP (tumor AFP), sourced from hepatocellular carcinoma (HCC)." (PMID 36768863, 2023). "Alpha-fetoprotein (AFP) can be used to differentiate intrahepatic CCA from hepatocellular carcinoma (HCC)." (PMID 36673043, 2023). "This study evaluated the impact of alpha-fetoprotein (AFP) testing frequency on survival rates in hepatocellular carcinoma (HCC) patients." (PMID 38201578, 2023). "For example, lapatinib was shown to be more effective for HER2-positive AFP-GC, and ramucirumab was reported to be more effective for AFP-positive hepatocellular carcinoma (HCC) than for AFP-negative HCC." (PMID 37354221, 2023). "In this study, we demonstrated that overall 51.2% of patients with hepatocellular carcinoma (HCC) had elevated alpha-fetoprotein (AFP) levels." (PMID 36831565, 2023). "Glycans of MUC1 (CA15-3), carbohydrate antigen (CA19-9) and alpha-fetoprotein (AFP) are monitored for management of breast cancer, pancreatic cancer, and hepatocellular carcinoma (HCC), respectively." (PMID 37773167, 2023). "Serum alpha-fetoprotein levels were still within the normal range at the recurrence time, in 53% of the patients who had recurrence after liver transplantation, but surprisingly were elevated in 47% of the patients at time of hepatocellular carcinoma recurrence." (PMID 37326153, 2023). "The high morbidity and mortality of hepatocellular carcinoma (HCC) has encouraged the search for new biomarkers to be used alongside alpha-foetoprotein (AFP) and imaging tests." (PMID 37024609, 2023). "The level of alpha-fetoprotein (AFP) was the most common biological marker used for the clinical diagnosis of HBV-related hepatocellular carcinoma (HCC)." (PMID 36363693, 2022). "A three-dimensional macroporous PAn-based electrode was developed for the sensitive detection of alpha-fetoprotein, which can be associated with several conditions, including hepatocellular carcinoma, metastatic disease affecting the liver, nonseminomatous germ cell tumor, or yolk sac tumor." (PMID 36671866, 2022).
hepatocellular carcinoma (continued). "The prognosis of hepatocellular carcinoma (HCC) varies considerably among patients with the same disease stage and characteristics, and only about two thirds show high levels of α-fetoprotein (AFP), a common prognostic indicator for HCC." (PMID 36258212, 2022). "In a hepatocellular carcinoma (HCC) mouse model, treatment with DCsEVs derived from alpha-fetoprotein (AFP)-expressing DCs elevated the numbers of INF-γ-expressing CD8 + T cells and decreased the secretion of IL-10 and TGF-β." (PMID 36167539, 2022). "Combination treatment of AFP-siRNA NPs and a low dose of sunitinib produced a synergistic effect in decreasing cell viability in an in vitro hepatocellular carcinoma (HCC) model." (PMID 36293521, 2022). "Alpha-fetoprotein (AFP) and core fucosylated AFP-L3 are closely correlated with hepatocellular carcinoma (HCC) and have been successfully used as clinical biomarkers for HCC diagnosis." (PMID 35163546, 2022). "We aimed to identify factors associated with elevated serum AFP in patients with non-hepatocellular carcinoma (HCC) and early-stage HCC and their influences on the performance of AFP for detecting early-stage HCC." (PMID 36016291, 2022). "Herein, we report a case of hepatic IPT misdiagnosed as hepatocellular carcinoma (HCC) due to the elevated serum levels of alpha-fetoprotein (AFP) and its Lens culinaris agglutinin-reactive fraction AFP lectin 3 (AFP-L3), and radiological findings." (PMID 33913027, 2021). "A hepatocellular carcinoma (HCC) prediction model (ASAP), including age, sex, and the biomarkers alpha-fetoprotein and prothrombin induced by vitamin K absence-II, showed potential clinical value in the early detection of HCC." (PMID 34412596, 2021). "The α-fetoprotein (AFP) model officially replaced the Milan criteria in France for liver transplantation (LT) for hepatocellular carcinoma (HCC) in January 2013." (PMID 34069594, 2021). "Alpha-fetoprotein (AFP) is one of the most common serum markers in the diagnosis of HCC, and its high expression in hepatocellular carcinoma cells makes it a promising target for vaccine-based therapy." (PMID 34513678, 2021). "Serum α-fetoprotein (AFP) is a gold standard biomarker for the diagnosis of hepatocellular carcinoma (HCC), however the specificity of AFP for HCC is relatively low and often does not distinguish HCC from other liver diseases." (PMID 33466384, 2021). "Alpha-fetoprotein (AFP) in hepatocellular carcinoma (HCC) cells can be used as indicators of disease diagnosis, recurrence and so on, which significantly changes the survival time of patients." (PMID 34905439, 2021). "The diagnostic rate of AFP-negative hepatocellular carcinoma is only 10.4%." (PMID 33889548, 2021). "It has been widely used as a specific cancer biomarker for hepatocellular carcinoma (HCC) since 1996 in Japan and 2005 in the United States because it is more specific than alpha-fetoprotein." (PMID 34948129, 2021). "PIVKA-II is often used for the auxiliary detection of patients with hepatocellular carcinoma (HCC) accompanied with Alpha-fetoprotein (AFP)." (PMID 35145947, 2021). "For prostate tissue, the probasin promoter (to drive E1A) and the enhancer element of prostate-specific antigen (PSA) (to drive E1B) were used and for hepatocellular carcinoma (HCC) the alpha-feto protein (AFP) promoter." (PMID 34638863, 2021). "Moreover, a recent study has showed that serum CK19 levels, associated to AFP and PIVKA-II, may be useful to stratify survival of patients with HCC in Patients with Hepatocellular Carcinoma, highlighting the importance of CK19 as a prognostic marker." (PMID 34677239, 2021). "Previous studies have found that alpha‐fetoprotein (AFP) can promote the proliferation of hepatoma cells and accelerate the progression of hepatocellular carcinoma (HCC)." (PMID 33090723, 2020). "For decades, hepatocellular carcinoma (HCC) screening relied primarily on ultrasound imaging and alpha‐fetoprotein (AFP)." (PMID 31693242, 2020).
hepatocellular carcinoma (continued). "Alpha-fetoprotein (AFP) has been widely used for many years as a serum marker for hepatocellular carcinoma (HCC)." (PMID 32736604, 2020). "AFP (alpha-fetoprotein) levels are increased during the development of HCC (hepatocellular carcinoma); nonetheless, it can also be produced by non-tumoral hepatocytes in conditions of high cell turnover." (PMID 32341704, 2020). "Positive AFP (>=200) was found in 29.4%, 42.8%, and 57.7% hepatocellular carcinoma (HCC) patients with size less than 3 cm, between 3 and 5 cm, and greater than 5 cm, respectively." (PMID 32458568, 2020). "Since the expression of AFP is highly specific for the liver, it was found elevated in hepatocellular carcinoma (HCC) patients and proposed as a tumor biomarker." (PMID 32365872, 2020). "Testing of AFP is useful in the diagnosis of hepatocellular carcinoma (HCC) only if the serum concentration of AFP is markedly elevated." (PMID 32341704, 2020). "Alpha‐fetoprotein has been widely applied as a tumour biomarker in detecting primary hepatocellular carcinoma (HCC), with high specificity." (PMID 33090723, 2020). "This classifier had a larger AUC than AFP in identifying small-sized tumors or early stage hepatocellular carcinoma and could detect α-fetoprotein-negative hepatocellular carcinoma in patients at risk." (PMID 33597967, 2020). "The diagnosis of hepatocellular carcinoma (HCC), the most frequent primary liver malignancy, is challenged by the silent course of the disease, fluctuating serum alpha-fetoprotein levels, and inconclusive radiological findings." (PMID 31581638, 2019). "The established biomarker for hepatocellular carcinoma (HCC), serum α-fetoprotein (AFP), has suboptimal performance in early disease stages." (PMID 31590436, 2019). "A markedly elevated AFP level suggests the presence of the disease, but concentrations of AFP may also be elevated in patients with hepatocellular carcinoma, germ cell tumors, as well as in benign liver tumors, including mesenchymal hamartoma and infantile hemangioma." (PMID 31817982, 2019). "In clinical practice, a rise of serum AFP is a well-known suitable serum tumor biomarker used to screen or monitor hepatocellular carcinoma (HCC), tumors of gonadal origin, or yolk sac tumors." (PMID 31915699, 2019). "However, not all biomarkers have appropirate sensitivity and specificity at the same time like AFP (alpha-fetoprotein), which has been widely applied in hepatocellular carcinoma detection clinically and monitoring development and prognosis of the disease at any time." (PMID 31727002, 2019). "It was also found that levels of alpha fetoprotein (AFP), a serological marker commonly seen in hepatocellular carcinoma, was maintained in both HCC organoids and parental tumors." (PMID 31773090, 2019). "Protein induced by vitamin K antagonist‐II (PIVKA‐II), in addition to alpha‐fetoprotein, is a useful tumor marker for diagnosis of hepatocellular carcinoma (HCC)." (PMID 31131509, 2019). "The AFP level increases in certain malignancies, especially in GCTs and hepatocellular carcinoma (HCC)." (PMID 31836006, 2019). "Ad CV890 was the first Ad5-specific developed for selectively targeting hepatocellular carcinoma (HCC) by using alpha-fetoprotein (AFP) as a tumor-specific promoter." (PMID 29534501, 2018). "Alpha-fetoprotein (AFP) has been recognized as a key regulator of cell proliferation in hepatocellular carcinoma (HCC)." (PMID 30301886, 2018). "A 43-year-old male patient presented with a mass lesion on the right liver lobe, segment 5, in radiological imaging and elevated alpha-fetoprotein levels (323 ng/mL) compatible with hepatocellular carcinoma (HCC)." (PMID 30317851, 2018). "The detection of alpha-fetoprotein (AFP) in plasma is important in the diagnosis of hepatocellular carcinoma (HCC) in humans." (PMID 30463232, 2018).